CD40 (CD40 molecule)
Diseases named in the same sentence as CD40 in open-access papers (continued):
Sharing a sentence is not in itself a finding about the gene and the disease.
tumor (continued). "In recent years, emerging evidence shows that CD40 plays a critical role in regulating antitumor effector macrophages with M1 polarization, leading to production of IFN-γ, IL-12, and nitric oxide (NO) to help mediate tumor killing." (PMID 32983125, 2020). "The presence of IL2 within the tumor through intratumoral IC may have a crucial role in driving this proposed T-dependent antibody response, as IL2 has been shown to be critical for CD40-mediated activation of naïve B cells by CD4 T cells." (PMID 32849544, 2020). "Furthermore, we have reported that the addition of the chemotherapy to agonistic CD40 and dual ICB significantly reduced the long-term survival of tumor bearing mice compared to immunotherapy alone." (PMID 33597954, 2020). "Evidence suggests that it is unlikely for CD40 monoclonal antibodies to exhibit substantial single-agent anti-tumor activity in PDAC patients; further studies are thus required to develop effective combinations of CD40 agonist therapy with chemotherapy, RT or other forms of immunotherapy." (PMID 32664564, 2020). "CD40 is expressed on monocytes and DCs and also B cells, platelets and non-hematopoietic cells and tumor cells." (PMID 35582441, 2020). "Growth of primary tumors receiving in situ Flt3L and TLR3/CD40 agonists was not altered by irradiating distant tumors, emphasizing the requirement for targeting the same tumor to achieve maximal tumor control by ISIM." (PMID 33110069, 2020). "Tumor vessels orchestrate T-cell recruitment during immune response, but the effect of CD40-stimulating immunotherapy on tumor endothelial cells has not been evaluated." (PMID 32231867, 2020). "Intratumoral Flt3L administration either with RT or with CD40/TLR3 stimulation did not alter tumor growth or survival; however, it did so only when combined with both procedures simultaneously." (PMID 33110069, 2020). "In this model there was an abscopal effect obtained with reduction in the size of the tumor not injected with anti-CD40 beyond that mediated by IL-15 alone." (PMID 32508818, 2020). "VEcadTRAP mice with B16.F10 tumors were treated peritumorally with agonistic CD40 mAb at day 11 and 14, and tumors were collected at day 15 when tumor sizes did not significantly differ between the groups." (PMID 32231867, 2020). "First, non-T cell inflamed, ‘cold' tumor can profit the usage of MEKi/CD40 Ab by elevating T cell numbers in the TME prior to resection." (PMID 33024933, 2020). "Additional weekly TLR3/CD40 stimulation once or twice following ISIM did not improve tumor response compared to mice treated with ISIM once in AT-3 tumor-bearing mice." (PMID 33110069, 2020). "Importantly, combined TLR3/CD40 stimulation was needed to increase the frequency of CD8+ TILs in AT-3 tumors, and tumor-specific Tet+ CD8+ T cells in the PB and 4T1 tumors." (PMID 33110069, 2020). "The administration of agonistic CD40 alone or in combination with RT leads to a significant increase in CD8+ and CD4 + T-cells infiltrating the tumour, and the combined approach may successfully induce T-cell dependent immunity." (PMID 33148287, 2020). "Treatment with agonist anti-CD40 mAbs induced TAM immunostimulatory and tumor inhibitory effects in mouse tumor models both alone and in combination with anti-CSF1R mAb, by enhancing antigen-presentation and pro-inflammatory cytokine production and priming naive T lymphocytes." (PMID 32456204, 2020). "We also examined whether RT needs to be delivered to the same tumor receiving injections of Flt3L and TLR3/CD40 agonists." (PMID 33110069, 2020). "The combination of anti-CD40 with anti-CSF-1R, which impairs the recruitment of new TAMs towards the tumor, was effective to treat “cold” preclinical tumor models, not responsive to immune checkpoint inhibitors (ICIs)." (PMID 33050070, 2020). "Moreover, circulating pDCs exhibited an altered response when compared to HD (% and/or MFI), while tumor‐infiltrating pDCs still upregulated CD80 and CD40 (MFI) upon R848 stimulation." (PMID 33282290, 2020).
tumor (continued). "Moreover, recent studies targeting CD40 together with VEGF and ANG2 blockade demonstrated significant benefit in mouse tumor models." (PMID 33217955, 2020). "On the other hand, CD40 stimulation without the parallel inclusion of a tumor antigen vaccination promoted the deletion of tumor specific cytotoxic CD8+ T cells." (PMID 32674488, 2020). "CD40 activated the NFκB pathway in cells depleted for LAPTM5 expression, promoting tumor growth and resistance to temozolomide, which could be overcome by NFκB inhibition." (PMID 32582531, 2020). "Administration of anti-CD40 in PDAC-bearing mice did not produce a significant change in the number of TAMs within the tumor, but a transitory change in macrophage activation (i.e., CD86 and MHC class II expression) was seen within 24-48 h of treatment." (PMID 35582441, 2020). "Quantification of (A) CD8+ T cells, (B) Ki-67+ CD8+ T cells and (C) Eomes+ CD8+ T cells in the lungs of tumor bearing CCSP-rtTA; TetO-EGFRL858R mice in the absence (−) and presence (+) of erlotinib, CD40 agonist or erlotinib plus the CD40 agonist for 2 weeks, (n = 4–6 mice per group)." (PMID 31291990, 2019). "Both groups showed increased T cell infiltration with CD40 stimulation, but neither reported long-term survivors, indicating that a CD40 agonist on its own is not enough to sustain a full anti-tumor immune response." (PMID 31396227, 2019). "Previous reports suggested that, despite the ability of soluble CD40 agonist to reduce RCC tumour size in vivo via immunocyte activation, RCC could be targeted more effectively by combining CD40-mediated immune activation with direct tumour CD40 signalling." (PMID 31815003, 2019). "The combination of anti-CD40 plus anti-CSF-1R antibodies has been evaluated in “cold” preclinical tumor models, not responsive to ICB." (PMID 31878087, 2019). "Combining CD40 agonists with nab-paclitaxel and gemcitabine further enhanced the T cell-mediated tumor destruction and generated immune memory, not seen with the gemcitabine combination alone." (PMID 31035449, 2019). "The potential of these CD40-activated B cells have been tested and validated in vivo in models of Human papillomavirus 16 (HPV16) E6 and E7 expressing TC-1 tumor, B16-F10 melanoma, E.G7 lymphoma, 4T1 breast tumor metastasis, sarcoma and in spontaneous non-Hodgkin’s lymphoma in dogs." (PMID 31086070, 2019). "Moreover, the activation of CD40 was beneficial to the secretion of VEGF, which promoted the formation of tumor blood vessels and the growth of tumors." (PMID 31708918, 2019). "CD40+ tumor cells interacting with CD154+ activated T cells promoted the secretion of TGF and the differentiation of Th17, which contributed to the proliferation of tumor cells." (PMID 31708918, 2019). "On evaluating gene array analysis of nonimmunogenic AgN2a cells compared to the parent immunogenic Neuro2a cell line, we identified down-regulation of several tumor immunosuppressive pathways, including PD-L1 (3.6-fold), CD47 (3.3-fold), CD74 (6-fold), and CD40 (2.3-fold)." (PMID 29377881, 2018). "Moreover, CD40 and TLR agonists act synergistically and the combination of these immunostimulants can significantly suppress B16-F10 tumor growth in mice." (PMID 30349530, 2018). "This was accompanied by reductions in tumor-associated CD8+ T cells expressing CD73 and IL-10 in elderly, but not young, IL-2/CD40-treated mice, relative to PBS controls." (PMID 30560130, 2018). "Furthermore, the synergy in the anti-CD40, CpG, and monophosphoryl lipid A (MPL) treatment was observed to activate TAMs via CD40/TLR9 ligation to kill tumor cells in vitro and inhibit tumor growth in vivo." (PMID 28660349, 2018). "In contrast, IL-2/CD40 induced reduced MHC-I and CD80 in young, but not elderly, tumor-associated CD11c+ cells." (PMID 30560130, 2018).
tumor (continued). "Antigen presentation is enhanced by anti-CD40, suggesting a means for development of autoreactive CD8 T cells, and ensuing destruction of healthy melanocytes by memory CD8 T cells recalled to the site of tumor rechallenge." (PMID 30245691, 2018). "Thus we confirm that memory T cells capable of preventing tumor recurrence are generated with combination of SBRT and intratumoral anti-CD40." (PMID 30245691, 2018). "Overall, 60% of mice treated with SRBs showed complete tumor regression during the observation period, compared to 10% for cohorts administered with anti-CD40 mAbs, but no SRB." (PMID 29594038, 2018). "Similarly, a poly(lactic-co-glycolic acid) nanoparticle loaded with poly I:C and coated with a CD40 agonist antibody was directed toward CD40 expressing CD11c+CD11b+F4/80− DCs in vivo, resulting in prolonged survival of B16-OVA-tumor bearing mice." (PMID 30349530, 2018). "In a similar manner, CTL-mediated antitumor immune responses were not seen in clinical trials with CD40 agonists in various cancers even with the addition of gemcitabine to increase tumor immunogenicity." (PMID 30158932, 2018). "Depletion of macrophages using F4/80 antibody in elderly, but not young mice, improved IL-2/anti-CD40 immunotherapy up to 78% tumor regression." (PMID 30459812, 2018). "The data above suggests elderly CD8+ T cells have reduced effector function and increased suppressive function, therefore we assessed the cytolytic capacity of young vs. elderly tumor-specific CD8+ T cells in TDLNs and tumors after two doses of IL-2/CD40 using an in vivo CTL assay." (PMID 30560130, 2018). "Taken together, this suggests that IL-2/CD40 alleviates suppressive CD11c+ cells in young, but not elderly tumors, likely contributing to reduced tumor responses to IL-2/CD40 by elderly mice." (PMID 30560130, 2018). "CD40 ligation is thought to enhance the immunogenicity of tumors, thus γδTc may secrete CD40L in order to better “see” tumor targets." (PMID 29963058, 2018). "It is noteworthy that in the ParvOryx01 study, CD40+ cells with a non-macrophage phenotype were observed in the tumor blood vessel lumen in patients who received H-1PV by intravenous infusion." (PMID 29244745, 2017). "The TC-1 and MC32 cells displayed no CD80, CD86 or CD40 surface expression, supporting the notion that CD80 is not directly associated with IFN-γ production and tumor progression." (PMID 28460461, 2017). "CD40, a cell surface molecule that belongs to the tumor necrosis factor (TNF) receptor family, was reported to participate in immune regulation and mediate tumor apoptosis." (PMID 28753978, 2017). "LPS-activated TLR4 signaling renders tumor cells resistant to CTL-induced killing, which might be attributed to increased expression of B7-H1, B7-H2, and CD40 and decreased expression of Fas." (PMID 28881826, 2017). "In addition, another NF-κB pathway, which is initiated by ligands such as RANKL, LTα, LTβ and LIGHT produced by TAMs, targets tumor-promoting genes like CXCL12 and VEGFC via receptors such as LTβR, CD40 and RANK." (PMID 28467800, 2017). "In addition, these antibodies also directly kill CD40-expressing cancer cells through ADCC, and eventually inhibit proliferation and growth of CD40-expressing tumor cells." (PMID 29387053, 2017). "One study showed that combination of an agonist CD40 antibody plus gemcitabine resulted in tumor regression in patients who were not eligible for tumor resection." (PMID 28753978, 2017). "Tumor growth inhibition following ISF35 treatment was abrogated in CD8 T cell-depleted mice, myeloid cell-depleted mice, and CD40 knockout mice, indicating a requirement for CD8+ T cells, myeloid cells, and CD40 signaling in host cells." (PMID 29129918, 2017). "In addition, post-NAC patients whose tumours had a GPR had a significantly increased expression of HLA-DR, CD40, CD86, and the LNHR CD197." (PMID 28913366, 2017).
tumor (continued). "The combination of sialidase treatment with tumor-antigen upload did not alter the expression of other co-stimulatory molecules, such as CD40, and of the chemokine receptor CCR7, when compared with fully sialylated MoDCs (results not shown)." (PMID 27203391, 2016). "Moreover, CD40 expression has been found on various tumor cells, and CD40/CD40L ligation can inhibit proliferation and induce apoptosis directly in tumor cells by activation of NF-κB, AP-1, CD95, or caspase-depended pathways." (PMID 27273619, 2016). "Despite high CD40 expression, anti-CD40 mAb therapy alone did not inhibit T241 tumor growth, while there was a trend towards reduced tumor size after sunitinib treatment." (PMID 27385210, 2016). "Tumour lysate pulsing resulted in a significant increase in the expression of MHC and costimulatory molecules as well as of CD83, a marker of phenotypical maturation, CD40 and CCR7." (PMID 26795765, 2016). "In contrast, the reduced accumulation of MDSCs noted in tumors treated with anti-CD40 mAb and sunitinib in our study was not related to hypoxia, tumor vessel pericyte coverage or vessel functionality since these parameters were similar in all treatment groups." (PMID 27385210, 2016). "The antibody response of the anti-CD40-treated SWHEL-positive mice to s.c. tumor challenge was indistinguishable from that to i.v. challenge." (PMID 27121060, 2016). "Additionally, we found that, compared to the tumor specific E6/E7 peptide vaccine, total tumor lysate induced higher expression of CD80 and CD40 on DCs that induced increased levels of IFNγ production upon interaction with host lymphocytes." (PMID 27223090, 2016). "We observed, that P2Et-treated mice had higher numbers of spleen conventional DCs (CD45+, CD220−, CD11c+) with increased surface expression of co-stimulatory molecules such as CD86, CD40, MHCII and CD70, suggesting that in vivo P2Et treatment actually enhances the immunogenicity of tumor cells." (PMID 27253407, 2016). "This indicated that CD40+ MDSC are preferentially recruited to and accumulated in tumor tissue." (PMID 26462153, 2015). "Therefore, our data not only show that CD40 has a role in the production of TGF-β from the tumor to suppress the immune system in the tumor microenvironment, but also has a novel mechanism in the increase of TGF-β production by CD40 stimulation." (PMID 25992978, 2015). "Stimulation of CD40 on APCs is through CD40L expression on helper CD4+ T cells which can activate and “license” the APCs to prime CD8+ T cell responses, and lead to enhanced tumor protection." (PMID 25825910, 2015). "This suggested that the recruitment and accumulation of CD40+MDSC in tumor tissue is not unique to a specific cancer type." (PMID 26462153, 2015). "In blood of tumor bearing Tgfbr1/Pten 2cKO mice, PD-1 blockade increased MHC-II+ and CD40+cells." (PMID 26573233, 2015). "We now show that CD40 protein is focally expressed on tumor cells in two of five primary LGSCs compared with no expression in eight primary SBOTs." (PMID 26313915, 2015). "We found that inflammatory E-cadherin + DCs were present only in anti-CD40-mediated innate immunity, not innate, adoptive and tumour immunity." (PMID 25651850, 2015). "In this study, we identified a novel mechanism by which CD40 promotes MDSC-mediated immune invasion and stimulates tumor growth by controlling the expression of chemokine receptor CXCR5 on MDSC, and modulating the recruitment of CD40+ MDSC that depends on CXCR5-CXCL13 signaling." (PMID 26462153, 2015). "Thus, it has been proposed that while classical NF-κb activation plays a pro-inflammatory role in macrophages during early stages of tumor growth, in established tumors signals such as lymphotoxin, BAFF or CD40, can lead to alternative NF-κb activation." (PMID 24723924, 2014). "Tumor metastases to lymph nodes were evaluated by H&E and CA125/CD40 staining." (PMID 24502459, 2014).
tumor (continued). "From our previous work, we know that Aldara-based TCI is not an ideal tumor vaccine since anti-tumor responses can be significantly augmented by additional stimulation such as UV exposure or CD40 triggering." (PMID 25025233, 2014). "The CD40/CD40L interaction on human and murine B cell lymphoma resulted in the arrest of cell cycle, which had a major significance for the induction and maintenance of tumor quiescent state." (PMID 25117071, 2014). "In murine nonepithelial tumours, CD-40/TLR-7 agonists have been utilized as adjuvants in vaccination with exogenous tumour antigen, which resulted in stronger and less toxic antitumour memory T-cell responses compared to monotherapy." (PMID 24475147, 2014). "In contrast, mice administered the SART3/CD40+GM-CSF gene-loaded DNA vaccine showed no development of lung metastasis (0/4 cases) and greater regression of tumor sizes." (PMID 25013909, 2014). "The apoptosis of the MDSCs was found to significantly increase following treatment with agonistic anti-CD40, and compared with the PBS treatment, the percentage of apoptotic tumor-infiltrating MDSCs increased from 71.37±2.68 to 79.09±3.29% (mean ± SEM; P=0.0352)." (PMID 25009656, 2014). "We have previously demonstrated that IL-2 based immunotherapy, in combination with CD40 agonist, results in synergistic anti-tumor effects which are CD8+ T-cell dependent but not antigen restricted and." (PMID 25119341, 2014). "In our preclinical systems or in human tumor-derived DCs, CD40 agonists alone had no measurable effect on DC activation in vivo." (PMID 24339824, 2013). "Therefore, we combined MRF/magnet treatment with anti-CD40/IL2 to treat disseminated disease and determine if greater anti-tumor responses and systemic immune activation can be achieved with this multi-approach therapy." (PMID 23133545, 2012). "Immunization with CD40-targeted Ad5-huPSMA alone or with non-targeted Ad5-huPSMA + Ad5-IFNγ similarly diminish tumor growth in animals challenged with RM-1-PSMA cells." (PMID 23056548, 2012). "This supports considerations to use ex vivo generated CD40-activated B cells as a promising alternative or additional APC for cellular immunotherapy, especially in settings where these immunosuppressive cytokines are present in tumor environment." (PMID 22592077, 2012). "In our studies, while modest direct anti-tumor effects were obtained using this approach, combination of MRF/magnetic field treatment with immunotherapy using suboptimal doses of agonistic anti-CD40/IL2 resulted in significantly greater and, importantly, systemic anti-tumor responses." (PMID 23133545, 2012). "Existing evidence suggests that TLR3 ligands can be used as anticancer agents and that a combination of CD40 and TLR agonists may synergistically act as immunostimulants by suppression of tumor growth in mice." (PMID 21737330, 2011). "Intraperitoneal injection of the anti-CD25 monoclonal antibody PC61 reduced Treg frequency in blood and tumors, but did not affect the frequency of tumor-infiltrating dendritic cells, or their expression of CD40, CD86 and MHCII." (PMID 21390236, 2011). "The efficient stimulation of tumor-specific T lymphocytes by DCs requires the presentation of tumor-derived epitopes on MHC class I and II molecules together with second signals (costimulatory molecules CD80, CD86, CD40) and proinflammatory cytokines such as IL-12 or TNF-α." (PMID 22110524, 2011). "We focused in those genes that were significantly differently methylated in the basal-like tumor subtype (HOXA9, SOX1, VAMP8, and TNFRS10D) and those that were significantly hypermethylated in the luminal B tumors (NPY, RASSF1, HS3ST2, DBC1, FGF2, CD40." (PMID 20920229, 2010). "CD40 is a phospholipoprotein belonging to the superfamily of type I TNF-receptors that expressed on both normal host cells (mainly DCs, B lymphocytes, macrophages and mast cells) and some tumor cells." (PMID 19591684, 2009).